MTOR (mechanistic target of rapamycin kinase)
Diseases named in the same sentence as MTOR in open-access papers (continued):
Sharing a sentence is not in itself a finding about the gene and the disease.
hyperreactivity (1 paper, 2022). "Luteolin can modulate OVA-induced airway bronchoconstriction and bronchial hyperreactivity, inhibit autophagy by activating PI3K/Akt/mTOR signaling and inhibit the Beclin-1-PI3KC3 complex." (PMID 35672815, 2022).
hypersensitivity pneumonitis (1 paper, 2013). Hypersensitivity pneumonitis (HP) is a pulmonary disease with symptoms of dyspnea and cough resulting from the inhalation of an antigen to which the subject has been previously sensitized. "We report here on the case of a patient presenting with hypersensitivity pneumonitis while being treated with everolimus, a mammalian target of rapamycin (mTOR) inhibitor." (PMID 24245774, 2013).
Hypoalbuminemia (1 paper, 2021). The concentration of albumin in the blood circulation is below the lower limit of normal. "Hypoalbuminemia, resulting from protein-losing enteropathy, was observed in all patients in the mTOR inhibitor therapy group prior to initiating therapy." (PMID 33822054, 2021).
Hypomagnesemia (1 paper, 2025). An abnormally decreased magnesium concentration in the blood. "Similarly, mammalian target of rapamycin (mTOR) inhibitors also produce hypomagnesemia in rats, which would be mediated, at least partly, by inhibition of epidermal growth factor (EGF)-induced regulation of TRPM6 expression, as demonstrated by in vitro studies in renal tubular epithelial cells." (PMID 40565121, 2025).
idiopathic pulmonary arterial hypertension (1 paper, 2015). A sporadic form of pulmonary arterial hypertension (PAH) characterized by elevated pulmonary arterial resistance leading to right heart failure. "Evidence has shown that mTOR contributes to the proliferation and survival of PASMCs in idiopathic pulmonary arterial hypertension (IPAH) in human and experimental PH as well." (PMID 26120832, 2015).
immunotoxicity (1 paper, 2025). "Notably, 44 targets, including EGFR, AKT1, PIK3R1, PTEN, and mTOR, were mapped to the PI3K-Akt signaling pathway, highlighting its potential association with celastrol-induced immunotoxicity." (PMID 40495892, 2025).
internalizing disorder (1 paper, 2023). A type of mental or behavioral disorder, typically in children and young adults, with symptoms including depression, anxiety and withdrawal. "RRAGA, which regulates the mTOR signaling cascade that may have a role in the antidepressant effects of NMDA antagonists, was the most interacting gene associated with GAD, highlighting the possible role of the mTOR pathway for internalizing disorder treatment." (PMID 37216417, 2023).
intestinal infection (1 paper, 2025). "This study investigated the role of the mechanistic targets of rapamycin (mTOR) and deoxycholic acid (DCA) on C. perfringens intestinal infection." (PMID 40284599, 2025).
invasive candidiasis (1 paper, 2019). "However, up to date the role of mTOR in invasive candidiasis is still unclear." (PMID 31668132, 2019). "For mice with severe invasive candidiasis, expression of LC3B and p62/SQSTM1 was higher in CD4+ T-cell-specific mTOR knockout mice but lower in CD4+ T-cell-specific TSC1 knockout mice compared with wild-type mice." (PMID 31668132, 2019). "Most interestingly, there was a significant difference in mortality between CD4+ T-cell-specific mTOR knockout and TSC1 knockout mice and wild-type mice with severe invasive candidiasis." (PMID 31668132, 2019).
invasive carcinoma (1 paper, 2015). A carcinoma that is not confined to the epithelium, and has spread to the surrounding stroma. "Of note, p-mTOR expression was high in most benign and pre-neoplastic lesions with reduced expression in DCIS and invasive carcinoma." (PMID 26657114, 2015). "Interestingly, high expression of p-mTOR was observed in all PNL with lower expression in DCIS and invasive carcinoma while the opposite expression pattern was observed for TOP2A." (PMID 26657114, 2015).
invasive ductal carcinomas (1 paper, 2014). "This preliminarily observation supports the role of PI3K in breast carcinogenesis and the potential therapeutic utility of PI3K/mTOR inhibitors in invasive ductal carcinomas." (PMID 25298748, 2014).
inverted urothelial papilloma (1 paper, 2023). An endophytic lesion in the urinary tract which shares several morphologic features with urothelial papilloma. "Additionally, through correlation analysis between the protein of HRAS and enriched pathways showed that HRAS protein might suppress mTOR pathway by inhibiting TSC2 ability in inverted urothelial papilloma." (PMID 37704624, 2023).
irritable bowel syndrome (1 paper, 2022). Irritable bowel syndrome (IBS) is a chronic functional condition of the lower gastrointestinal (GI) tract characterized by abdominal pain or discomfort and disordered bowel habit (diarrhea, constipation, or fluctuation between the two). "Through network pharmacology analysis, JM25-1 showed a therapeutic possibility for irritable bowel syndrome (IBS) with predictive targeting on PI3K/AKT/mTOR signaling." (PMID 36678544, 2022).
ischemic cardiomyopathy (1 paper, 2023). Ischemic cardiomyopathy is a cardiomyopathy in which a weakness in the muscle of the heart due to inadequate oxygen delivery to the myocardium with coronary artery disease being the most common cause. "For instance, a single cell transcriptomic analysis on cardiac macrophages in CS and ischemic cardiomyopathy has recently been reported, focusing mostly on the upregulation of mTOR signaling in CS." (PMID 37576111, 2023).
keratoconus (1 paper, 2021). A degenerative, structural disorder of the eye, characterized by a cone-shaped protrusion of the cornea. "The top canonical pathways that were most significant to keratoconus stroma were EIF2 and mTor signalling, oxidative phosphorylation, and mitochondrial dysfunction." (PMID 33865984, 2021).
language delays (1 paper, 2024). "While no major congenital abnormalities have been reported in the cases we reviewed, language delays and developmental abnormalities were noted in some children, which could either be a reflection of the underlying TSC pathology or a subtle effect of mTOR inhibitor exposure." (PMID 39518472, 2024).
Left ventricular dilatation (1 paper, 2025). Enlargement of the chamber of the left heart ventricle. "In the embryonic and neonatal stages, the systemic or cardiac-specific mTOR knockout mice die in embryonic and neonatal stages mainly due to left ventricular dilatation and malfunction." (PMID 40092733, 2025).
Lesch–Nyhan disease (1 paper, 2023). "Interestingly, in HPRT KO iPSC-derived neurons—a cellular model of Lesch–Nyhan disease—the dopaminergic differentiation is impaired due to an inhibition of the mTOR pathway." (PMID 37834379, 2023).
Leukoencephalopathy (1 paper, 2017). This term describes abnormality of the white matter of the cerebrum resulting from damage to the myelin sheaths of nerve cells. "Taken together, activation of a maladaptive ISR, mTOR pathway and disruption of lipid metabolism homeostasis secondary to mitochondrial dysfunction might be critical pathological mechanisms in p32-related leukoencephalopathy." (PMID 29123152, 2017).
Lewy body dementia (1 paper, 2025). A progressive form of dementia characterized by the presence of protein deposits called Lewy bodies in the midbrain and cerebral cortex, and loss of cholinergic and dopaminergic neurons. "Although direct experimental evidence in Lewy body dementia remains limited, the convergence of Wnt signalling abnormalities and mTOR hyperactivation across AD, FTD, and PD supports a shared vulnerability mechanism in neurodegeneration." (PMID 41477452, 2025). "Although direct evidence in Lewy body dementia remains limited, the convergence of Wnt dysregulation and mTOR hyperactivation across the Alzheimer’s and other neurodegenerative spectra provides a mechanistic basis for the hypothesis that this pathway plays a wider role in neurodegenerative risk." (PMID 41477452, 2025). "However, no definitive mechanistic study to date has evaluated Wnt/mTOR interplay in dementia with Lewy Bodies or α-synucleinopathies, signalling an important gap for future research." (PMID 41477452, 2025).
Leydig cell tumor (1 paper, 2022). A sex cord-stromal tumor occurring in the testis and rarely in the ovary. "Next, we also showed that in experimentally-induced Leydig cell tumors (LCT) in mouse testis, estradiol may be controlled only via mTOR, similarly as in human LCT, however by different mechanisms." (PMID 35740412, 2022).
lipoprotein deficiency (1 paper, 2023). "Although starvation stress may activate the mTOR pathway, which can suppress ferroptosis, the levels of phospho-S6K were unaffected by lipoprotein deficiency 29,30." (PMID 37714840, 2023).
Lissencephaly (1 paper, 2025). A spectrum of malformations of cortical development caused by insufficient neuronal migration that subsumes the terms agyria, pachygyria and subcortical band heterotopia. "Treating MDS organoids with the mTOR inhibitor everolimus partially rescued these phenotypes, highlighting mTOR signaling as a key mediator of disease progression and a potential therapeutic target in LIS1-lissencephaly." (PMID 40806509, 2025).
Loeys-Dietz syndrome (1 paper, 2020). Loeys-Dietz syndrome is a rare genetic connective tissue disorder characterized by a broad spectrum of craniofacial, vascular and skeletal manifestations with four genetic subtypes described forming a clinical continuum. "The AD phenotype in Loeys-Dietz syndrome was recapitulated in the mouse model, concomitant with aberrant activation of the mTOR pathway, dysregulated cell proliferation, and loss of the SMC contractile phenotype, all of which were restored by rapamycin." (PMID 32397282, 2020).
lower limb ulcers (1 paper, 2025). "The present study therefore aims to investigate the activation of the mTOR pathway in APS-associated lower limb ulcers." (PMID 40141392, 2025).
lung adenoma (1 paper, 2022). A benign, well circumscribed epithelial neoplasm that arises from the bronchus or the lung parenchyma. "In lung adenoma cells, Mito-LND treatment significantly decreased the expression of genes associated with complex I, complex II, OXPHOS, and AKT/mTOR/p70S6K signaling, and increased the expression of genes associated with autophagy, supporting our previous results." (PMID 35626143, 2022).
lung adenosquamous carcinoma (1 paper, 2020). "For example, we found that two group-7 molecules (Gr-7A & Gr-7B), which both produced long-term cell toxicity and appeared to inhibit mTOR, reduced the ATP content by ∼40–50% in a human lung adenosquamous carcinoma cell line HTB178 (data not shown)." (PMID 31879284, 2020).
Lyme disease (1 paper, 2025). Lyme disease (named after the towns in the USA where the disease was first identified) is a bacterial infection caused by Borrelia burgdorferi. "Direct human evidence of mTOR dysregulation in Lyme disease is lacking; however, Borrelia modulates immunometabolic programs, including PI3K/Akt/mTOR, in human immune cells ex vivo, and Borrelia-induced cytokine production depends on glycolysis/HIF-1α." (PMID 41462744, 2025).
malabsorption syndrome (1 paper, 2026). A syndrome resulting from the inadequate absorption of nutrients in the small intestine. "Anorexia, malabsorption syndromes, ectopic ACTH, drugs (thiazide diuretics, insulin, granulocyte growth factor, glucocorticoids), antineoplastic drugs (cisplatin, ifosfamide, anti-EGFR agents, mTOR inhibitors, eribulin, abiraterone)." (PMID 41601884, 2026).
malaise (1 paper, 2025). A feeling of general discomfort or uneasiness, an out-of-sorts feeling. "Our prior research in both human subjects and a mechanistically informed animal model identified chronic mTOR activation and subsequent autophagy impairment as potential drivers of ME/CFS pathogenesis, particularly in relation to post-exertional malaise (PEM), a hallmark symptom of the disease." (PMID 40502741, 2025).
Marfan syndrome (1 paper, 2021). A disorder of the connective tissue. "Such simulations appear to be particularly useful given that single-cell RNA sequencing reveals considerable variability across otherwise similar SMCs in both health and disease, including Marfan syndrome and mTOR hyperactivation." (PMID 34898595, 2021).
Menstrual disorder (1 paper, 2019). Category of disorders related to menstruation. "Although the cause of menstrual disorders is still not very clear, some researchers think it may be caused by mTOR inhibitors disturbed hormone levels." (PMID 31586081, 2019).
mucinous tumors (1 paper, 2024).
multifocal choroiditis (1 paper, 2010). Multifocal choroiditis (MFC) is an inflammatory disorder characterized by swelling of the eye (called uveitis) and multiple lesions in the choroid, a layer of blood vessels between the white of the eye and the retina. "We recently reported treating a patient with multifocal choroiditis associated with choroidal neovasculization (CNV) with rapamycin, an mammalian target of rapamycin (mTOR) inhibitor." (PMID 20157617, 2010).
multiple system atrophy (1 paper, 2022). Multiple system atrophy (MSA) is a neurodegenerative disorder characterized by autonomic failure (cardiovascular and/or urinary), parkinsonism, cerebellar impairment and corticospinal signs with a median survival of 6-9 years. "Sirolimus and novel mTOR inhibitors are currently being tested in clinical trials in PD and multiple system atrophy (MSA) patients (clinicaltrials.gov: NCT03589976; anzctr.org.au: ACTRN12619000372189)." (PMID 35842725, 2022).
muscle disorders (1 paper, 2017). "Downregulation of mTOR is a shared feature in other muscle disorders." (PMID 28130275, 2017).
myositis (1 paper, 2023). "Sirolimus (rapamycin) consists of an inhibitor of the mammalian target of rapamycin (mTOR) pathway and an immunosuppressant drug used in myositis." (PMID 36615886, 2023).
myotonic dystrophy (1 paper, 2022). An inherited progressive disorder affecting the muscles. "Although autophagy outcomes have been controversial among the studied DM1 models, there is evidence that AKT/mTOR pathway dysregulation is involved in the pathogenesis of myotonic dystrophy." (PMID 36230978, 2022).
Nail dystrophy (1 paper, 2019). Onychodystrophy (nail dystrophy) refers to nail changes apart from changes of the color (nail dyschromia) and involves partial or complete disruption of the various keratinous layers of the nail plate. "Inhibitors of mTOR, which affect autophagy and other processes, are associated with nail dystrophy, pointing to dysregulation of cornification-associated autophagy as a potentially relevant side-effect of these drugs." (PMID 30552537, 2019).
Neonatal sepsis (1 paper, 2020). Systemic inflammatory response to infection in newborn babies. "For example, microRNA-300/NAMPT regulates inflammatory responses through activation of the AMPK/mTOR signaling pathway in neonatal sepsis." (PMID 32908583, 2020).
nephrosclerosis (1 paper, 2024). Hardening of the kidney due to infiltration by fibrous connective tissue (fibrosis), usually caused by renovascular diseases or chronic hypertension. "Klotho supplementation reduces BP, renal angiotensinogen, Ang II, and HIF-1, mammalian target of rapamycin (mTOR), Akt, and medullary fibrosis in adult SHR-SP with nephrosclerosis." (PMID 39765782, 2024).
nervous system injuries (1 paper, 2024). "The Akt/mTOR pathway undergoes a dramatic increase in signaling activity after injury, and has become a focus for drug development for the treatment of central nervous system injuries." (PMID 38066401, 2024).
neurodevelopmental disabilities (1 paper, 2017). "However, mTOR inhibitors have not been adequately evaluated or approved for the treatment of neurodevelopmental disabilities in TSC, especially in young infants." (PMID 28288694, 2017).
neuronal tumor (1 paper, 2022). Neuronal brain tumors are an uncommon group of central nervous system tumors that arise from cells with neuronal differentiation. "SEGAs are considered mixed glio-neuronal tumors, with mTOR activity and presence of inflammation markers." (PMID 34709498, 2022).
non-alcoholic fatty liver (1 paper, 2024). A benign form of fatty non-alcoholic fatty liver disease where the disease has not yet progressed to the inflammation of liver. "This study investigated the effects of Rg5 on the phenotype of NAFLD induced by HFD in mice, including its key role in inhibiting the development of non-alcoholic fatty liver through the LKB1/AMPK/mTOR signaling pathway and the gut–microbiota–liver axis." (PMID 38542753, 2024).
Nystagmus (1 paper, 2023). Rhythmic, involuntary oscillations of one or both eyes related to abnormality in fixation, conjugate gaze, or vestibular mechanisms. "However, none of the patients with pathogenic MTOR variants were reported to have nystagmus." (PMID 40217313, 2023).
ocular tumors (1 paper, 2025). "Secondly, there is growing interest in targeting metabolic signaling pathways, including PI3K/AKT/mTOR, AMPK, and HIF-1α, as a therapeutic approach to disrupt the metabolic dependencies of ocular tumors." (PMID 40994549, 2025).
oral cavity tumors (1 paper, 2020). "This pathway dependence is also being investigated clinically in multiple trials using direct PI3K and/or mTOR inhibitors in oral cavity, as well as by the use of metformin, which blocks mTOR indirectly, for oral cavity tumors prevention in patients with potential premalignant lesions." (PMID 32370133, 2020).
oral epithelial dysplasia (1 paper, 2020). "For example, an immunohistochemical investigation revealed a greater expression of the activated forms of key proteins of the AKT/mTOR pathway such as AKT and mTOR in oral epithelial dysplasia (OED) than OSCC and non-dysplastic oral tissues (NDOT)." (PMID 32384682, 2020).
orchitis (1 paper, 2021). Inflammation of one or both testes due to viral or bacterial infections. "However, the role of the mTOR pathway remains arcane with respect to potential alterations of the BTB during bacterially-induced orchitis." (PMID 33679734, 2021). "Collectively, this study showed an association between abnormal activation of the mTOR-signaling pathway and BTB impairment during UPEC-induced orchitis, which may provide new insights into a potential treatment strategy for testicular infection." (PMID 33679734, 2021).
oropharyngeal tumors (1 paper, 2013).
otitis media (1 paper, 2024). Inflammation of the anatomical structures of the middle ear, which is most often caused by an infectious process. "This conclusion is reinforced by our literature review, which supports the involvement of mTOR, LC3II/I, PI3K, beclin-1, FLIP, Akt, and Rubicon in the pathogenesis of otitis media." (PMID 38391409, 2024).
ovarian granulosa cell tumor (1 paper, 2019). A granulosa-stromal cell tumor that arises from the ovary. "At this point, we see that studies on the potential overactivity of mTOR pathway in granulosa cell ovarian tumors are scarce." (PMID 30592193, 2019). "There is a strong need for studies on expression of mTOR and p-mTOR in human ovarian granulosa cell tumor cultures." (PMID 30592193, 2019). "In our study, we investigated the expression of mTOR and phospho-mTOR in granulosa cell ovarian tumor sections in order to better understand the molecular genetic features of granulosa cell ovarian tumors and determine whether mTOR inhibitors could be used in treatment." (PMID 30592193, 2019).